MYC (MYC proto-oncogene, bHLH transcription factor)
Diseases named in the same sentence as MYC in open-access papers (continued):
Sharing a sentence is not in itself a finding about the gene and the disease.
cancer (continued). "Altered MYC has been linked to treatment resistance in several types of cancer." (PMID 38909137, 2024). "Induction of c-MYC is a well-established oncogenic event, associated with cell growth, proliferation, and survival; thus, its upregulation represents a crucial node in cancer biology." (PMID 38429845, 2024). "Furthermore, deletion or mutation of the E242-E261 amino acids in the MYC protein enhances the transcriptional function of MYC by altering its aggregation capacity and subsequently promoting cancer cell proliferation." (PMID 39343006, 2024). "Finally, MYC plays a role in the regulation of division and cell growth, and its overexpression has been linked to the development and progression of cancer." (PMID 38891892, 2024). "Gene set enrichment analysis (GSEA) Hallmark pathway analysis using a STAD dataset from TCGA revealed that TAGLN2 is involved in many signaling pathways associated with cancer, including apoptosis, hypoxia, MYC targets, KRAS signaling, and the reactive oxygen species pathway." (PMID 39168971, 2024). "Cancer initiation, maintenance and progression have been linked to disruptions in MYC function." (PMID 38637125, 2024). "However, the loss of regulatory mechanisms of MYC initiates cancer by modulating the expression of genes related to cell growth and proliferation, as well as inducing changes in the cancer microenvironment." (PMID 37568727, 2023). "If we consider the MYC T244 example, it appears possible that substrates governed by low-affinity CPDs may be more strongly impacted by cancer-associated FBXW7 missense mutations, such as those that alter residue R689." (PMID 37681873, 2023). "MYC as a cancer-causing gene expresses three proteins: MYC-1, MYC-2, and MYC-3." (PMID 36897696, 2023). "This study created an awareness of the therapeutic effects of saponin in cancer therapy since MYC is a super transcriptional factor whose expression is upregulated in over 70% of cancer types and it is known that MYC is the hallmark of cancer initiation and maintenance." (PMID 37233456, 2023). "Several cancer‐associated genetic polymorphisms are located within the surrounding non‐coding region of MYC, implicating that these variants may alter regulatory elements of MYC expression." (PMID 36366788, 2023). "Although it is milder than homozygous deletion ofCry2, we hypothesized that reducedCry2 rhythmicity could alter MYC protein accumulation and contribute to enhanced cancer risk caused by circadian disruption." (PMID 37811199, 2023). "This suggests that MYC-dependent cancers may be susceptible to inhibitors of PRMT5 and other splicing regulators that may be overexpressed in MYC-driven cancer cells." (PMID 36979496, 2023). "c-MYC is the oncoprotein that has been implicated in various cancers, including CaP." (PMID 37895357, 2023). "Moreover, promoters of many oncogenes and other cancer-associated genes (e.g., MYC, KRAS) have the PQS and G4 which appear to regulate their expression." (PMID 36768357, 2023). "Glutamine addiction extends from the context of MYC, and mutations in KRAS —a key gene related to the stability and activity of c-MYC protein— in cancer cells similarly cause dependence on exogenous glutamine for cellular growth and proliferation, as does MYC amplification." (PMID 36959802, 2023). "Uncontrolled proliferation of cancer cells is due to mutations, deletions, or amplifications in genes (oncogenes) encoding for proteins that regulate cell growth and division, such as transcription factors, for example, c-MYC." (PMID 36979947, 2023). "Dysregulation of MYC expression or activation has been linked to many human cancers." (PMID 36911524, 2023). "MYC is a well-studied oncogene that is implicated in many types of cancers." (PMID 37664059, 2023). "Furthermore, CTCF has been proposed to regulate CDK9 recruitment at the MYC locus and has been implicated in cancer-specific transcriptional dysregulation." (PMID 36998071, 2023).
cancer (continued). "It would be interesting to test whether these features, including the tipping point and the explosive heterogenicity, would be applied to AML driven by other mutations and other cancers driven by MYC." (PMID 37130348, 2023). "In the present study, we explored computational simulations through bioinformatics analysis and identified the overexpression of c-Met/GSK3β/MYC/CCND1 oncogenic signatures that were associated with cancer progression, drug resistance, metastasis, and poor clinical outcomes in CRC." (PMID 36672275, 2023). "Metabolic rewiring supports cancer cell proliferation and growth, and our findings suggest that loss of circadian oscillation by MYC may be a feature of metabolic rewiring." (PMID 37639465, 2023). "Of the three l‐MYC‐positive patients, two patients died of cancer and one died of another cause." (PMID 36694106, 2023). "As MYC can orchestrate all aspects of cellular metabolism, its altered regulation plays a central role in these processes, such as the Warburg effect, and is a well-established hallmark of cancer development." (PMID 37443779, 2023). "Gene set enrichment analysis revealed downregulation of terms associated with neuronal development and differentiation, while upregulated terms were mainly associated with ribosome biogenesis and ribosomal RNA (rRNA) synthesis and processing, a characteristic hallmark for MYC-driven cancers." (PMID 37919824, 2023). "Furthermore, as a m6A code reader, IGF2BPs plays a carcinogenic role in cancer cells, possibly by stabilizing methylated mRNAs of cancer-causing targets, such as MYC." (PMID 37807062, 2023). "As expected, the complete loss of MYC almost completely inhibited the growth of cancer cells." (PMID 37444499, 2023). "For instance, high MYC expression is associated with aggressive biological behavior in cancers." (PMID 37649078, 2023). "However, new evidence suggests a crucial role of some gene mutations (PTEN, PIK3CA, FGFR2, ARID1A, and MYC) in cancer progression from endometrial hyperplasia." (PMID 38201599, 2023). "Additionally, mutations that increase the activity of WREs that regulate oncogenes such as MYC are also associated with increased cancer risk." (PMID 36423688, 2023). "The vast majority of cancer-associated SNPs are located in the regulatory regions, including enhancers and lncRNAs upstream/downstream of MYC, while pathogenic point mutations in the MYC gene itself are very rare in cancer." (PMID 37443779, 2023). "In the same vein, precocious increase in transcriptional output could cause disease, as is the case for MYC-driven cancers and Down syndrome-associated leukaemia, and was recently found in many cancers to associate with poor prognosis." (PMID 37833256, 2023). "In this paper, we report on identification of BRAFV600E, CCND1, and MYC mutations in a patient with synchronous triple primary malignant neoplasms, including malignant melanoma (MM), papillary thyroid carcinoma (PTC), and clear-cell renal cell carcinoma (ccRCC)." (PMID 37221610, 2023). "Loss of FAT1 binding capacity for the key classical WNT pathway protein β-Catenin was caused by loss of FAT1 expression in cancer and therefore resulted in β-Catenin translocation to the nucleus and downstream expression effects such as regulation of target genes MYC and Cyclin D1." (PMID 36653435, 2023).
cancer (continued). "Deregulated MYC is also implicated in breast and prostate cancers, which belong to the most frequent malignancies in women and men, respectively, with one-eighth of the entire human population developing one of these highly heterogeneous cancer forms." (PMID 36969025, 2023). "MYC regulates expression of genes associated with cell cycle, apoptosis, proliferation, and cellular differentiation, as well as strongly alters metabolism of cancer cells and stimulates ribosome and mitochondrial biogenesis." (PMID 37519063, 2023). "Finally, we used GSEA to analyse the association of PES1 with the MYC targets V1 pathway in nine cancer types, including HNSCC." (PMID 36217758, 2023). "Since many tumors depend on continuous MYC expression, this oncoprotein is one of the crucial drivers in human cancers, from which many are associated with a poor clinical outcome, indicating that deregulated MYC contributes to or drives the genesis of multiple tumors." (PMID 36969025, 2023). "Similarly, terms associated with estrogen signaling, cancer progression, MYC, and SMARCE1-dependent targets were oppositely regulated." (PMID 37082578, 2023). "Interestingly, cancer cells with mutations in oncogenes, such as MYC, are less prone to adapt to fasting conditions, remaining highly proliferative." (PMID 35908046, 2022). "It was also associated with cancer pathways (e.g., MYC targets) (left)." (PMID 35572559, 2022). "The association between MYC and immune suppression has been described in a variety of cancers." (PMID 36291770, 2022). "Omomyc is a MYC dominant negative that has shown potent antitumor activity in multiple cancer cell lines and mouse models, regardless of their tissue of origin or driver mutations, by impacting on several of the hallmarks of cancer." (PMID 36860495, 2022). "Therefore, the MYC signaling pathway is one of the most important drivers of dysregulated polyamine metabolism-associated cancers." (PMID 35327428, 2022). "MYC is dysregulated in more than 50% of cancers of all tissues but is especially implicated in prostate cancers and B-cell cancers such as Burkitt’s lymphoma, which is driven by chromosomal translocation of MYC." (PMID 35594991, 2022). "While missense mutation resulting in the substitution of residues regulating MYC stability has been established as a potential mechanism promoting oncogenic MYC activity, there is a paucity of information regarding other somatic cancer-associated substitutions." (PMID 36018850, 2022). "Deregulated expression of the MYC family of oncogenes/transcription factors MYC, MYCN, and MYCL (here collectively referred to as “MYC”) occurs in more than half of all cancers, and is often strongly associated with aggressive tumors, resistance to therapy, and poor prognosis." (PMID 36874405, 2022). "Abnormal expression of MYC is generally associated with a poor cancer prognosis." (PMID 35847359, 2022). "The lin28B/Let-7c/MYC axis is associated with the occurrence of many cancers." (PMID 36057607, 2022). "Additionally, we also interrogated the effect of two common cancer-associated MYC substitutions within and proximal to MB2: F138C and S146L." (PMID 36018850, 2022). "Besides PC, RIPK2 is frequently genetically altered in several other cancers, its overexpression is associated with shorter overall survival in nine cancer types, and its activity scores are highly correlated with MYC activity scores across 32 cancer types." (PMID 35115556, 2022). "The ability of HPV integration to alter expression of nearby human genes (within 500 Kb) has been demonstrated in both OPSCC and UCSCC with recurrent integration sites identified near genes implicated in cancer such as MYC, MYB, PVT1, RAD51B, EMBP1, CD274/PD-L1, and SOX2." (PMID 36139648, 2022).
cancer (continued). "In summary, this study shows that CNVs in regions of the genome that encode certain cancer drivers (for example, MYC and PTEN) are truly early events, occurring in tissue regions currently unknown to and therefore ignored by pathologists." (PMID 35948708, 2022). "Notably, we observed recurrent stabilization of mRNAs that encode epithelial-mesenchymal transition (EMT) proteins and MYC targets across multiple cancer types." (PMID 35987939, 2022). "In addition to MCM2 to MCM7, six downstream oncogenic targets of c-MYC implicated in cancer survival and metabolism including PSMA1, PSMA6, PSMB2, HDAC2, LDHA and SPRING were positively correlated with IFITM3 in 71 GC specimens using the Cho dataset." (PMID 35941699, 2022). "The MYC oncogene family, including c-MYC, N-MYC and L-MYC, encodes a group of nuclear phosphoproteins that take effect in cell proliferation, apoptosis and progression of cancers." (PMID 35761419, 2022). "MYC proteins are oncogenes that are implicated in 70% of cancers and are involved in promoting drug resistance in bladder, pancreatic and prostate cancer, but also in haematological malignancies such as multiple myeloma (MM)." (PMID 35883678, 2022). "Endogenous factors refer to changes in oncogenes or tumor suppressor genes that enhance the expression of PD⁃L1 in cancer cells, such as overexpression of MYC, mutation of the RAS oncogene and activation mutation of the EGFR, which can upregulate PD-L1 expression and thus promote immune escape." (PMID 35279217, 2022). "In addition, c-MYC overexpression is associated with human cancers, including breast cancer, colon cancer, glioma, medulloblastoma, pancreatic cancer, prostate cancer, and hepatocellular carcinoma." (PMID 35629138, 2022). "Therefore, the down-regulation or complete loss of the MYC oncogene can reverse the uncontrolled replicative characteristic of cancer cells." (PMID 34448104, 2022). "In vitro downregulation of MYC in cancer cells has been associated with reduced cell proliferation." (PMID 35879772, 2022). "Moreover, MYC-signaling activation is also subject to complex post-transcriptional regulation and is highly associated with cancer cell differentiation." (PMID 36299592, 2022). "In cancer models, elevated MYC oncogene levels are associated with aggressive tumors." (PMID 35740532, 2022). "In the following section, we will discuss the roles of MYC in inducing apoptosis in more detail, and then review the mechanisms underlying the co-operativity between these two important signalling pathways in cancer." (PMID 33799592, 2021). "MYC activation is thus considered as a hallmark of cancer initiation and maintenance." (PMID 33572152, 2021). "MYC is also involved in cell proliferation and differentiation, transcriptionally activating cell cycle regulators and repressing cell cycle inhibitors and is implicated in the development of cancer drug resistance." (PMID 33996588, 2021). "Further studies strongly linked c-MYC to cancer, marking it as a bona fide human oncogene." (PMID 33718147, 2021). "In addition, c-MYC is associated with the aggressive nature of cancers and modulates the expression of several miRNAs in various malignancies." (PMID 34336814, 2021). "In addition, we observed that MIR4435-2HG expression was positively associated with MYC activity (which was reported to play prominent roles in glycolysis regulation) across the five cancer types." (PMID 33627136, 2021).
cancer (continued). "In cancer cells, MYC is overexpressed due to aberrations in MYC locus, including polymorphisms in MYC regulatory sequences, copy number variations, and chromosomal translocations, or by aberrant transduction pathways of MYC activation and repression." (PMID 33801599, 2021). "This molecule is able to downregulate MYC expression in CBP-deficient cancers, promoting apoptosis." (PMID 33801599, 2021). "With one third of all cancer deaths linked to excess MYC proteins, these molecules could be key targets for anti-cancer drugs." (PMID 33416496, 2021). "We also included the most common MYC mutation in cancer, T58I/A/P/N." (PMID 34676047, 2021). "It is noteworthy, that some of the transcription factors which have been previously linked to EZH2 activation, albeit in other cancer entities, underlie transcriptional control by NFATc1 (MYC, STAT3) or represent well-characterized NFATc1 partner proteins (STAT3, ELK1)." (PMID 34943970, 2021). "First described in colon cancer, CCAT1 and CCAT2 both originate from the 8q24.21 chromosomal region, in close proximity with the MYC gene (500 kb and 300 kb upstream, respectively) and encompassing the cancer risk-associated rs6983267 single nucleotide polymorphism (SNP)." (PMID 34830370, 2021). "Dysregulation of MYC expression is associated with the pathogenesis of many human cancers." (PMID 34930894, 2021). "All these events seem to link MYC expression to cancer-associated rearrangements." (PMID 33801599, 2021). "The MYC oncogene, which encodes c-MYC (or MYC) basic helix–loop–helix (and leucine zipper) transcription factor, is a critical regulator of glucose and glutamine metabolism central to the Warburg effect, and highly associated with several human cancers." (PMID 34831287, 2021). "First, the COSMIC database identifies three cancer-associated mutations within the MYC HBM, all of which convert the subprime ‘QHNY’ motif to ‘EHNY’, which matches the perfect HBM consensus and closely resembles the gain-of-function VP16 HBM we used in this study." (PMID 33416496, 2021). "They propose an interplay between the CLOCK/BMAL1 and the cancer associated MYC and HIF-1α, in which suspension of the circadian clock could alter the oscillation of glycolysis." (PMID 34067971, 2021). "MYC is frequently deregulated in human cancers and associated with poor prognosis." (PMID 34116677, 2021). "Furthermore, there is growing evidence that cancer stemness is associated with the expression of OCT3/4, SOX2, c-MYC, and other genes involved in the self-renewal regulation of malignant cancer cells, as well as normal stem cells." (PMID 34440702, 2021). "One option for treating cancers linked to MYC proteins could be to target proteins that work alongside MYC proteins, such as the protein HCF-1, which can attach to MYC proteins." (PMID 33416496, 2021). "Notably, many oncogenes and other cancer-associated genes (e.g. c-MYC, VEGF) have G4 sequences that appear to regulate their expression making these sites targets for pharmaceutical intervention." (PMID 34541539, 2021). "Human cancers frequently overexpress MYC, but simultaneously may harbor additional mutations, copy number alterations and translocations." (PMID 33760847, 2021). "Mechanistically, the longevity of the effects of combined HDAC and mTOR inhibition may be mediated through interference with MYC, as MYC-driven cancer cell lines seem to be particularly susceptible to this drug combination." (PMID 33658498, 2021). "The MYC oncogene causes many human cancers and is activated by FOXP3 in NSCLC." (PMID 34503105, 2021). "The MYC genes, which consist of three paralogs encoding transcription factors C-MYC, L-MYC and N-MYC, are among the most frequently deregulated driver genes in human cancer." (PMID 34445617, 2021).